LGR4 (leucine rich repeat containing G protein-coupled receptor 4)
Diseases named in the same sentence as LGR4 in open-access papers (continued):
Sharing a sentence is not in itself a finding about the gene and the disease.
breast carcinoma (11 papers, 2015 to 2025). "Study identified that LGR4 expression was associated with poor prognosis in breast cancer." (PMID 35140734, 2021). "LGR4 is over-expressed in breast cancer and it has been associated with poor prognosis." (PMID 33946652, 2021). "In breast cancer, whereas one study found that LGR4 correlated with the expression of EMT markers, both the epithelial marker E-cadherin was downregulated and the mesenchymal markers Slug and vimentin were upregulated." (PMID 40469438, 2025). "In contrast, Li demonstrated that LGR4 promotes breast cancer metastasis by downregulating MGP expression." (PMID 41395115, 2025). "A positive correlation between LGR4 expression and the occurrence of bone metastasis in breast cancer was found by bioinformatics." (PMID 40469438, 2025). "Apart from its cognate receptor RANK, RANKL also interacts with the leucine-rich repeat containing G protein-coupled receptor 4 (LGR4) that stimulates breast cancer initiation and metastasis through Wnt signaling." (PMID 37568820, 2023). "Depletion of LGR4 resulted in a reduction of SOX2+ breast cancer stem cells, disruption of the Wnt/β-catenin signaling pathway, and a decrease of the tumorsphere formation ability." (PMID 33946652, 2021). "In an ESR1-luciferase reporter assay using T47D (a human breast cancer cell line), LGR4 knockdown also inhibited the luciferase activities induced by RSPO1." (PMID 32749219, 2020). "Interestingly, in studies of breast cancer, LGR4 has been found to promote DKK1 secretion, which promotes breast cancer bone metastasis." (PMID 40469438, 2025). "However, the current studies on the role of LGR4 in tumor bone metastasis are mainly focused on breast cancer and MM." (PMID 40469438, 2025). "Furthermore, in breast cancer and multiple myeloma, LGR4 promotes tumor cell metastasis to bone tissue by activating related signaling pathways." (PMID 40469438, 2025). "Here, we report that PRA mediates the P4-induction and UPA-inhibition of the expression of both WNT5A and LGR4, suggesting an essential function of PRA-mediated, P4 triggered- breast cancer cell proliferation." (PMID 26474308, 2015). "In addition, LGR4 can modulate the FAK-SRC pathway and it regulates the actin dynamics and cell adhesion of breast cancer cells, thus promoting cell migration." (PMID 33946652, 2021). "At present, there are also many other treatments for breast cancer bone metastasis, such as microRNA, the small-molecule antagonist adrenomedullin, combination therapy, such as OPG in combination with tamoxifen, LGR4 target therapy, interferon (IFN)-based therapies, and others." (PMID 29416737, 2018).
colon cancer (10 papers, 2012 to 2024). "LGR4 is also strongly implicated in the survival of stem cells in the gut and in colon cancer development." (PMID 24205130, 2013). "LGR4 expression was shown to be increased in approximately half of colon cancer cases with high levels being associated with more severe metastasis." (PMID 22615920, 2012). "Taken together, these reports suggest that LGR4 acts as a promoter of invasion and metastasis in colorectal cancer, and it modulates colon cancer stem cells by the activation of the WNT/β-catenin signaling pathway." (PMID 33946652, 2021). "CircLGR4, through LGR4, increased colon cancer stem cell self-renewal and enhanced their invasive and metastatic capacity." (PMID 33946652, 2021). "Recent evidence showed that LGR4 regulates colon cancer stem cells by interacting with the circLGR4-peptide ligand and inducing the Wnt signaling pathway." (PMID 33946652, 2021). "Strikingly, the role of Lgr4 in cancer has been recently recognized, and Lgr4 has been reported to promote tumor metastasis through a PI3K-Akt-Erk-β-catenin-Tcf signaling axis in colon cancer." (PMID 27187360, 2016). "Overall, these results indicate that LGR4 expression was increased in the majority of colon cancers, consistent with previous findings based on mRNA analysis." (PMID 24205130, 2013). "We have previously shown by qPCR that colon cancer cell line HT29 cells expressed moderate levels of LGR4 while HCT116 had negligible amounts, which is also consistent with the microarray expression data in CCLE (Cancer Cell Line Encyclopedia)." (PMID 24205130, 2013). "RSPO1 stimulation of LGR4 potentiates Wnt signaling which is generally oncogenic, and overexpression of RSPO2 and RSPO3 is associated with carcinogenesis in human colon cancer as well as in mouse models of breast and colon cancer." (PMID 24205130, 2013). "To understand potential roles and mechanisms of LGR6 in oncogenesis, we profiled a panel of colon cancer and uterine cancer cell lines for expression levels of LGR4–6 and RSPO1–4." (PMID 22615920, 2012). "To examine the effect of LGR6 on growth and migration of cancer cells, we attempted to overexpress LGR6 WT and insGRS mutant in SW620 cells which have relative low expression of LGR4–6 and are routinely used as a model of colon cancer studies." (PMID 22615920, 2012). "Overall, the expression pattern of LGR4 in adult human tissues strongly supports its role in the physiological functions of kidney, testis, and breast, and potentially in the development of some colon cancers." (PMID 24205130, 2013). "LGR4 was clearly upregulated in a significant fraction of human colon cancer." (PMID 24205130, 2013). "Strong LGR4-IR was observed in some colon tumors as shown by the representative samples." (PMID 24205130, 2013). "Next, the antibodies were further analyzed on endogenous LGR4 using colon cancer cell lines." (PMID 24205130, 2013). "Correlations between LGR6 mRNA expression levels and expression levels of LGR4, LGR5, CEA and CXCL16 mRNAs in lymph nodes of colon cancer patients." (PMID 38715790, 2024). "Next, we examined the expression of LGR4 in human colon cancers and their normal adjacent tissues with 7E7 given the finding of recurrent RSPO2/3 gene fusions in human colon cancer." (PMID 24205130, 2013). "Lgr4/GPR48 is known to be involved in the canonical Wnt/β-catenin signaling pathway, and β-catenin cooperates with active Foxo3a to regulate the metastasis of colon cancer cells." (PMID 34298649, 2021).
colorectal cancer (10 papers, 2015 to 2025). A primary or metastatic malignant neoplasm that affects the colon or rectum. "Upregulation of GPR48/LGR4 expression, associated with downregulation of P27kip1, promotes invasiveness and metastasis in colorectal carcinoma cells." (PMID 29383135, 2017). "Recent research has demonstrated that monoclonal antibodies targeting LGR4 can specifically induce ferroptosis and overcome drug resistance in colorectal cancer by inhibiting the LGR4-WNT signaling pathway." (PMID 38816377, 2024). "A recent study showed that the circLGR4-derived peptide activates LGR4 to enhance WNT/β-catenin in colorectal cancer." (PMID 33946652, 2021). "Specifically, a study revealed that LGR4 was upregulated in colorectal cancer (CRC) and enhanced tumor metastasis by PI3K/Akt and MAPK/ERK1/2-mediated β-catenin/TCF signaling." (PMID 35140734, 2021). "The potential effects of LGR4 and its ligand in the treatment of inflammatory bowel disease, chemoradiotherapy-induced gut damage, colorectal cancer, and diabetes are also discussed." (PMID 26379625, 2015). "Additionally, LncGata6 recruited the NURF complex onto the promoter of Ehf to enhance its transcription, which elevated the expression of LGR4/5 to activate Wnt signaling, thus promoting the progression of colorectal cancer." (PMID 35140734, 2021). "They showed that the transcriptional activity of LGR4 is mediated by E2F in colorectal cancer." (PMID 33946652, 2021). "In addition, GPR48/LGR4 contributes to tumor metastasis by stimulating β-catenin/TCF signaling, and is associated with poor prognosis in colorectal cancer." (PMID 29383135, 2017). "In colorectal cancer, LGR4 overexpression upregulates the ferroptosis inhibitor SLC7A11 via Wnt-dependent mechanisms, fostering chemoresistance, while LGR4 blockade induces lipid peroxidation to restore drug sensitivity." (PMID 41345330, 2025). "In addition, LGR4 can mediate the signaling of β-catenin/TCF via regulation of GSK-3β phosphorylation through the MAPK/ERK1/2 and PI3K/Akt pathways in colorectal cancer." (PMID 33946652, 2021).
lung carcinoma (6 papers, 2017 to 2023). "LGR4 is abundantly expressed in lung cancer adenocarcinomas and tumors co-expressing both LGR4 and the RSPO3 ligand exhibit high aggressiveness." (PMID 33946652, 2021). "Overexpression of mir-449b reduced proliferation and the invasive capacity of lung cancer cell lines by decreasing LGR4 expression, thus, highlighting the role of LGR4 in migration and invasion processes." (PMID 33946652, 2021). "Previously, we showed that LGR4 was highly expressed in the lung cancer cell line A549 and RNA-seq expression data showed no expression of LGR5, LGR6, RNF43, and ZNRF3 in A549 cells." (PMID 37402772, 2023). "For other IRGs, such as LGR4, GDF10, GREM1, IL20RB, INHA, VIPR1, and ADM2, they had been verified to participate in carcinogenesis and affect patients’ prognoses in other cancers, although the relevant studies were rare in lung cancer." (PMID 33386920, 2021).
multiple myeloma (6 papers, 2018 to 2025). "Recent studies have found that LGR4 is highly expressed in multiple myeloma cells but largely unexpressed in plasma cells." (PMID 40469438, 2025). "At the same time, aberrantly expressed LGR4 empowers Wnt signaling in multiple myeloma by hijacking osteoblast-derived R-spondins, thereby promoting the development of multiple myeloma." (PMID 40469438, 2025). "Some cancers, e.g. multiple myeloma employ atypical overexpression of LGR4 on plasma cells (a type of B cell responsible for antibody production, in the bone marrow)." (PMID 35707461, 2022). "Multiple myeloma cells were found to have aberrant LGR4 signaling, and thus were capable of increased sensitivity to Wnt signaling." (PMID 29867053, 2018). "However, when overexpressing LGR4, plasma cells take over RSPOs produced by pre-osteoblasts, to over-activate Wnt signaling and this leads to progression of multiple myeloma." (PMID 35707461, 2022). "LGR4 interacts with and regulates the expression of TGF-β1, activates the TGF-β1/Smad signaling pathway and promotes multiple myeloma progression." (PMID 40469438, 2025). "Then it is doubtful whether LGR4 can bind to RANKL and thus promote MMBD.A 20-year-old study found that myeloma cells can secrete the factor DKK1, which affects the function of osteoblasts and osteoclasts, leading to the development of MMBD." (PMID 40469438, 2025).
inflammatory bowel disease (5 papers, 2013 to 2025). A spectrum of small and large bowel inflammatory diseases of unknown etiology. "LGR4-deficient mice exhibited higher susceptibility to inflammatory bowel disease induced by DSS (dextran sodium sulfate) and higher mortality due to impaired proliferation and differentiation of intestinal crypts and Paneth cells during tissue regeneration." (PMID 33946652, 2021). "In addition, LGR4-null mice also showed decreased Wnt signaling, suggesting that LGR4/Wnt signaling acts as a protective factor against inflammatory bowel disease." (PMID 33946652, 2021). "Intestinal epithelial cell proliferation was reduced in Lgr4−/− mice, with an 80% decrease in crypt Paneth cells, suggesting that Lgr4 plays a crucial role in intestinal stem cell maintenance; Lgr4 also appears to play a protective role against inflammatory bowel disease." (PMID 23840940, 2013). "This study reported improved experimental colitis in LGR4 mutant mice through inhibition of glycogen synthase kinase 3 beta (GSK-3β), indicating an important role of LGR4 in inflammatory bowel disease (IBD) recovery." (PMID 41333132, 2025).
acute myeloid leukemia (4 papers, 2021 to 2026). Acute myeloid leukemia (AML) is a group of neoplasms arising from precursor cells committed to the myeloid cell-line differentiation. "LGR4 is also essential for leukemic stem cell self-renewal in acute myeloid leukemia (AML) patients." (PMID 33946652, 2021). "In acute myeloid leukemia (AML), GADD45A, a stress-responsive downstream effector of the LGR4 pathway, plays a protective role by restraining leukemia-initiating activity and enhancing oxidative defense." (PMID 41601687, 2026).
diabetes (4 papers, 2015 to 2025). "If Lgr4 loss in humans similarly induces insulin resistance, it could exacerbate the risk of developing diabetes, particularly type-2 diabetes, which is characterized by insulin resistance and impaired insulin secretion." (PMID 39033139, 2024). "Insights from our work suggest that Lgr4 loss could elevate diabetes risk through mechanisms that involve effects on insulin resistance, glycemic levels, and the production and secretion of insulin." (PMID 39033139, 2024). "Yet, the role of LGR4 in many cell types (e.g. pancreatic beta cells) and diseases (e.g., diabetes) remains to be elucidated." (PMID 35707461, 2022). "Further studies on the functions and signaling mechanisms of the LGR4 and Rspo proteins will facilitate the development of therapeutic strategy for human diseases, such as IBD, CRC, and diabetes, by targeting Rspo-LGR4." (PMID 26379625, 2015).
gastric cancer (4 papers, 2019 to 2022). A primary or metastatic malignant neoplasm involving the stomach. "We evaluated the immunoexpression of LGR4 and β-catenin in primary gastric carcinomas, lymph node metastases and histologically normal gastric mucosa in the surgical margins of gastric primary tumours." (PMID 30803215, 2019). "In gastric cancer, LGR4 is a potential stem cell marker, and may be involved in the activation of β-catenin similar to LGR5 and LGR6." (PMID 30803215, 2019). "Some recent studies have investigated LGR4 in stomach cancer." (PMID 30803215, 2019). "In summary, LGR4 is a potential biomarker of stem cells in normal gastric mucosa and carcinomas of the stomach, not specific to cancer cells and positively associated with cell proliferation." (PMID 30803215, 2019). "LGR4 is a likely biomarker of stem cells in the normal gastric mucosa and carcinomas of the stomach, not specific to cancer cells and positively associated with cell proliferation." (PMID 30803215, 2019). "Researchers discovered communications between CAFs and gastric cancer cells via integrin receptor interactions with collagen, fibronectin, thrombospondin 1 (THBS1) ligands, and leucine rich repeat containing G protein-coupled receptor 4 (LGR4)- R-spondin 3 (RSPO3), which regulate stemness." (PMID 36154923, 2022).
osteoarthritis (4 papers, 2020 to 2025). A noninflammatory degenerative joint disease occurring chiefly in older persons, characterized by degeneration of the articular cartilage, hypertrophy of bone at the margins and changes in the synovial membrane. "In synovial tissue, LGR4 expression levels are significantly diminished in mice with traumatic osteoarthritis, and overexpression of LGR4 ultimately inhibits the proliferation of synovial cells and reduces joint inflammation." (PMID 40149584, 2025). "One study even suggests that upregulating LGR4 may help alleviate the development of joint inflammation in traumatic osteoarthritis." (PMID 40469438, 2025).
osteosarcoma (4 papers, 2018 to 2024). A usually aggressive malignant bone-forming mesenchymal neoplasm, predominantly affecting adolescents and young adults. "LGR4 was shown to be expressed by osteosarcoma cells and, in several forms of cancer, implicated in the tumor progression, migration and metastatic processes (for instance." (PMID 30355966, 2018). "A previous study showed that LGR4 could be up-regulated by Stat3 in human osteosarcoma cells, but reduced when Stat3 was deficient." (PMID 38292169, 2024). "Overexpression of LGR4 has also been observed in glioblastoma, osteosarcoma, gastric, ovarian, and thyroid carcinomas." (PMID 33946652, 2021). "Stat3 could elevate LGR4 expression by binding to LGR4 promoter, thereby regulating osteosarcoma progression." (PMID 35140734, 2021). "Consequently, in osteosarcoma cells, LGR4 may have a similar function in response to its ligand RANKL." (PMID 30355966, 2018).
ovarian carcinoma (4 papers, 2019 to 2025). A malignant neoplasm originating from the surface ovarian epithelium. "Moreover, high levels of LGR4 have been associated with poor overall survival and recurrence-free survival in ovarian cancer." (PMID 33946652, 2021). "Subsequent investigations revealed that ALYREF promotes platinum resistance in ovarian cancer cells by activating the Wnt/β-Catenin pathway via the NSUN2/ALYREF/LGR4 signaling axis." (PMID 41345330, 2025). "This interaction enhances the stability and nuclear export of LGR4 mRNA, thereby contributing to platinum resistance in ovarian cancer." (PMID 41345330, 2025). "In our study, we observed a puzzling phenomenon: binding site mutation and overexpression of ALYREF alter the level of m5C modification in the CDS region of LGR4 mRNA in platinum-resistant ovarian cancer cells." (PMID 41345330, 2025). "Validation in cisplatin-resistant ovarian cancer cells revealed that only LGR4 was significantly upregulated." (PMID 41345330, 2025). "Taken together; these results suggest that RSPO2 prevents the endocytosis and lysosome-mediated degradation of LGR4 in ovarian cancer cells." (PMID 36217544, 2022). "A recent study showed that LGR4 regulates the epithelial cancer stem cell subpopulation in ovarian cancer." (PMID 33946652, 2021). "Though understudied in ovarian cancer, LGR4 may similarly regulate platinum resistance." (PMID 41345330, 2025). "Collectively, these data demonstrate that NSUN2 establishes CDS-specific m5C marks on LGR4 mRNA to enable ALYREF recognition, thereby promoting cisplatin resistance in ovarian cancer." (PMID 41345330, 2025). "To investigate the functional relationship between ALYREF and LGR4, we knocked down or overexpressed ALYREF in ovarian cancer cells." (PMID 41345330, 2025). "Knockdown of LGR4 resulted in the inhibition of stem cell transcription factors (POU5F1 and SOX2), reduction of cell surface markers (CD133, ALDH1A2), and suppression of tumor growth and metastasis of ovarian cancer cell lines." (PMID 33946652, 2021). "Mechanistically, LGR4 and ELF3 form a reciprocal regulatory loop positively modulated by WNT7B/FZD5 via the non-canonical Wnt signaling pathway, thus maintaining the stemness of ovarian cancer cell lines." (PMID 33946652, 2021). "RSPO2 did not affect the mRNA level of LGR4 in either of these ovarian cancer cell lines." (PMID 36217544, 2022).